RAB37 (RAB37, member RAS oncogene family)
Description:
The small GTPases Rab are key regulators of intracellular membrane trafficking, from the formation of transport vesicles to their fusion with membranes. Rabs cycle between an inactive GDP-bound form and an active GTP-bound form that is able to recruit to membranes different sets of downstream effectors directly responsible for vesicle formation, movement, tethering and fusion. Acts as an organizer for autophagosome biogenesis in a GTP-dependent manner. Involved in retinal homeostasis by autophagy regulation.
Tractability: Antibody: its Gene Ontology location is reachable by antibodies, with high confidence. PROTAC: ubiquitination databases record sites on it; its protein half-life has been measured.
Gene: Protein-coding gene on chromosome 17 (74,670,578 to 74,747,337, forward strand). Ensembl gene ENSG00000172794.
Subcellular location: Cytoplasmic vesicle; Cell projection, cilium
Pathways (Reactome):
Immune System: Neutrophil degranulation
Metabolism of proteins: RAB geranylgeranylation
Gene Ontology:
Molecular function: G protein activity; GTPase activity; protein binding; GTP binding
Biological process: positive regulation of autophagy; regulation of exocytosis; regulation of eye photoreceptor cell development
Cellular component: endoplasmic reticulum-Golgi intermediate compartment; azurophil granule membrane; cytoplasmic vesicle; photoreceptor connecting cilium; plasma membrane; specific granule membrane; cilium
Genetic constraint (gnomAD): Loss-of-function variants: 29 observed, 31.76 expected, observed/expected ratio (o/e) 0.91, 90% interval 0.68 to 1.25. The upper end of that interval is the gene's LOEUF score, 1.25, which puts it in group 5 of 6, group 1 being the genes least tolerant of losing a copy. Missense variants: 292 observed, 288.86 expected, observed/expected ratio (o/e) 1.01, 90% interval 0.92 to 1.11. Synonymous variants: 127 observed, 116.56 expected, observed/expected ratio (o/e) 1.09, 90% interval 0.94 to 1.26.
Homologues: Orthologues: pig RAB37 (96% identical), mouse Rab37 (94% identical), dog RAB37 (91% identical), guinea pig RAB37 (91% identical), chimpanzee RAB37 (90% identical), rabbit RAB37 (90% identical), macaque RAB37 (78% identical), rat Rab37 (78% identical), tropical clawed frog rab37 (70% identical). Paralogues in human: RAB26 (65% identical), RAB8B (44% identical), RAB10 (44% identical), RAB8A (43% identical), RAB2B (40% identical), RASEF (40% identical), RAB13 (39% identical), RAB44 (39% identical), RAB27A (39% identical), RAB1B (38% identical), RAB2A (38% identical), RAB1A (38% identical), and 56 more.
Diseases named in the same sentence as RAB37 in open-access papers:
RAB37 is named in the same sentence as 35 diseases in open-access papers, as found by Europe PMC text mining. Sharing a sentence is not in itself a finding about the gene and the disease. The quoted sentences say what the papers report.
lung carcinoma (22 papers, 2015 to 2025). "These clinical data suggest that tumors from lung cancer patients with poor survival rates or poor chemo-responses are characterized by a distinct immunosuppressive TME with a high level of infiltrating Rab37+ST2L+CD206+ tumor-associated M2 macrophages." (PMID 38778059, 2024). "By performing analysis in a lung cancer patients’ cohort, they showed that a low expression of Rab37, and thus of SFRP1, is associated with poor prognosis and high Oct4 expression, a well-known stemness marker." (PMID 34072080, 2021). "Rab37 acts as a metastasis-related tumor suppressor gene in lung cancer, and low mRNA expression of Rab37 is significantly associated with lung metastasis." (PMID 25823663, 2015). "Moreover, we conducted correlation analysis, relating intratumoral Rab37+ST2L+CD206+ tumor-associated M2 macrophage stain intensity to clinicopathological parameters of 48 lung cancer patients." (PMID 38778059, 2024). "Additionally, univariate Cox regression indicated that lung cancer patients with high tumor-infiltrating Rab37+ST2L+CD206+ tumor-associated M2 macrophage profile had increased death risk." (PMID 38778059, 2024). "Together, these clinical results demonstrated for the first time that tumors from advanced lung cancer patients with poor survival was characterized by a distinct immunosuppressive TME with a high level of stromal CHI3L1+Rab37+ associated with tumor infiltrating M2 macrophages." (PMID 34987649, 2022). "However, a subgroup of lung cancer patients with preserved Rab37 level was linked to high mortality." (PMID 29312551, 2017). "We therefore tested whether Rab37 dysregulation was associated with PKCα level in clinical lung cancer specimens." (PMID 29312551, 2017). "Clinically, patients with Rab37+/PD-1+/TIM3+/CD8+ tumor-infiltrating T cells expression profile correlate with poor outcome in lung cancer model." (PMID 38321486, 2024). "Lung cancer patients with high levels of intratumoral Rab37+PD-1+TIM3+CD8+ T cells are found to be significantly associated with poor prognosis." (PMID 38321486, 2024). "In early-stage patients, ST2L and Rab37 showed low colocalization in CD206-labeled tumor-associated M2 macrophages, contrasting with increased colocalization in advanced lung cancer." (PMID 38778059, 2024). "These clinical data suggest that tumors from lung cancer patients with poor survival are characterized by a distinct immunosuppressive TME with a high level of tumor-infiltrating Rab37+/PD-1+/TIM3+/CD8+ T cells." (PMID 38321486, 2024). "This study reveals that except Rab7a, five Rab proteins, Rab8a, Rab11b, Rab27a, Rab35, and Rab37, were highly expressed in the purified AP of lung cancer cells (CL1‐5‐Q89L) with a high secretory tendency (Q) (column 4 vs. column 3)." (PMID 38804615, 2024). "Patients suffering from lung cancer with metastasis and poor survival demonstrates that decreased expression levels of Rab37 are consistent with low TIMP1 expression in lung tumors." (PMID 38695990, 2024). "RAB37 dependent secretory autophagy participates in TIMP1 secretion in lung cancer both in vitro and in vivo." (PMID 38804615, 2024). "The tumor regions enriched in PD-1+/TIM3+/CD8+ T cells also positively correlated with high Rab37+ stains in lung cancer patients." (PMID 38321486, 2024). "Next, the Kaplan–Meier analysis results showed that increased intratumoral stain intensity of PD-1+/CD8+/Rab37+ and PD-1+/TIM3+/CD8+/Rab37+ T cells correlated with poorer overall survival and disease-free survival of lung cancer patients." (PMID 38321486, 2024). "Our results reveal for the first time that Rab37 mediates PD-1 intracellular trafficking and PM presentation to sustain T cell exhaustion in lung cancer." (PMID 38321486, 2024). "The Kaplan–Meier analysis revealed that higher infiltrating Rab37+ST2L+CD206+ tumor-associated M2 macrophages correlated with poorer overall and disease-free survival in lung cancer patients." (PMID 38778059, 2024).
lung carcinoma (continued). "A high level of tumor-infiltrating Rab37+ST2L+CD206+ M2 macrophages independently predicted clinical outcomes in lung cancer patients." (PMID 38778059, 2024). "The results suggested that tumor-infiltrating PD-1+/TIM3+/CD8+/Rab37+ T cells served as a potential biomarker for lung cancer prognosis (AUC: 0.79, P < 0.0001)." (PMID 38321486, 2024). "We recently reported that Rab37 is involved in secretory autophagy to mediate TIMP1 secretion in lung cancer cells." (PMID 38778059, 2024). "We previously reported that Rab37 is hypermethylated in lung cancer, thereby leading to downregulation of Rab37." (PMID 38321486, 2024). "Rab37 mediates the exocytosis of tissue inhibitor of metalloproteinase 1 (TIMP1) in a nucleotide-dependent way to disrupt MMP9 migration in lung cancer." (PMID 38695990, 2024). "Univariate Cox regression analysis indicated that lung cancer patients with high tumor-infiltrating Rab37+/PD-1+/TIM3+/CD8+ T cell profile or aggressive M status showed poor survival outcome." (PMID 38321486, 2024). "Clinically, Rab37+/ST2L+/CD206+ tumor-infiltrating M2 macrophages correlate with advanced-stage lung cancer patients with poor response to chemotherapy." (PMID 38778059, 2024). "We are the first to report that autophagy plays a promoting role in TIMP1 secretion and metastasis in a Rab37-dependent manner in lung cancer cells and the lung-to-lung mouse model." (PMID 36457117, 2022). "Initially, we compared the levels of TIMP1 secretion and LC3-II expression (representing autophagic activity) using CL1-5 lung cancer cell lines harboring either stably expressed active-form Rab37 (Q89L) or the control (Vector)." (PMID 36457117, 2022). "Lung-to-lung metastasis mouse model was used to clarify the role of autophagy and Rab37 in lung cancer." (PMID 36457117, 2022). "The results confirmed that autophagy participates in active-form Rab37-mediated TIMP1 secretion as well as in metastasis of lung cancer cells and the lung-to-lung mouse metastasis model." (PMID 36457117, 2022). "Low Rab37, low TSP1 expression alone with high angiogenesis marker CD31 in lung cancer patients is associated with poor disease outcome." (PMID 35927755, 2022). "High PKCα/Rab37/tissue inhibitor of metalloproteinase-1 (TIMP1) expression profile correlated with worse progression-free survival in patients with lung cancer." (PMID 36358843, 2022). "Lung cancer patients with low level of Rab37 in tumor tissue show reduced secreted TIMP1 level in intratumor tissue and correlate with distant organ metastasis and poor prognosis." (PMID 35927755, 2022). "The lung-to-lung metastasis mice model was prepared using Rab37 knockdown lung cancer H460 cells (Rab37 KD H460)." (PMID 36457117, 2022). "SFRP1 is secreted by Rab37 in a GTP-dependent manner to restrain sphere forming ability of lung cancer cells by inhibiting Wnt/β-catenin transactivation." (PMID 35927755, 2022). "To understand how Rab37 expression in the stromal cells impacts lung cancer progression, we generated whole-body Rab37 KO mice in C57BL/6 background." (PMID 34093869, 2021). "We have previously reported dysregulation of Rab37 in lung cancer cells, whereas the roles of Rab37 in tumor-infiltrating immune cells and cancer immunotherapy are unclear." (PMID 34093869, 2021). "Of interest, the release of ST2 in Rab37 exosomes skewed M1 macrophage polarization leading to reduced tumor growth in models of lung cancer." (PMID 34447383, 2021). "In conclusion, we found that Rab37-mediated exocytosis of IL-6 from macrophages promotes PD-1 upregulation in T cells via the Rab37/IL-6/STAT3 transcription axis to support lung cancer progression." (PMID 34093869, 2021). "The A549 lung cancer cell line was chosen because its intrinsic Rab37 was expressed at a higher level than other lung cancer cells." (PMID 34093869, 2021).
lung carcinoma (continued). "Multiplex fluorescence immunohistochemistry was performed to detect the protein level of Rab37, IL-6 and PD-1 and localization of the tumor-infiltrating immune cells in allografts from mice or tumor specimens from lung cancer patients." (PMID 34093869, 2021). "Low Rab37 protein expression levels in lung cancer indicate poor prognosis in patients with lung cancer at different stages and lymph node metastasis." (PMID 34141705, 2021). "Among this group of genes, aberrantly methylated in other human cancers were CCR6 in oral cancer and chronic lymphocytic leukemia, RAB37 in lung cancer, ZNF521 in breast cancer, and CDX1 in gastric cancer, esophageal SCC, and in colon cancer." (PMID 32961999, 2020). "It was demonstrated that Rab-37 suppresses lung cancer metastasis by mediating TIMP1 (tissue inhibitor of metalloproteinase) exocytosis, which inactivates extracellular matrix metallopeptidase 9 (MMP9) and suppresses cell invasion signalling." (PMID 31370342, 2019). "For example, RAB37 is identified as a tumor suppressor and frequently downregulated by promoter hypermethylation in lung cancer and nasopharyngeal cancer." (PMID 31511502, 2019). "Collectively, these in vitro and in vivo results confirmed that Rab37 knockdown promotes lung cancer stemness properties." (PMID 30158579, 2018). "Taken together, our findings suggest that Rab37-mediated SFRP1 exocytic transportation exert inhibitory effects on lung cancer stemness." (PMID 30158579, 2018). "Lung cancer patients with low Rab37, low SFRP1 protein expressions coincide with high Oct4 expression in their tumors." (PMID 30158579, 2018). "To this end, we established Rab37 knockdown H460 lung cancer cells (shRab37#1 and shRab37#2) and sh-control H460 stable cell line (shCtrl)." (PMID 30158579, 2018). "Here, we provide compelling evidence to demonstrate the suppressive role of Rab37 in lung cancer stemness." (PMID 30158579, 2018). "Overexpression of Rab37 inhibited self-renewal abilities and down-regulated expression of stemness genes and Wnt-related genes in lung cancer cells and limit number of xenotransplantation models." (PMID 30158579, 2018). "Our finding of Rab37-mediated exocytosis of SFRP1 in cancer cells provides a new insight into the role of Rab37 small GTPase in lung cancer stemness." (PMID 30158579, 2018). "To determine the functional role of Rab37 in lung cancer stem-like cells, we performed three-dimensional (3D) sphere culture using lung cancer cells manipulated for Rab37 expression." (PMID 30158579, 2018). "Together, these results verified the inhibitory role of Rab37 in Wnt/β-catenin signaling and stemness properties in lung cancer." (PMID 30158579, 2018). "Targeting Rab37-SFRP1-Wnt axis in select lung cancer patients with low Rab37 or low SFRP1 expression for SFRP1 protein treatment can be a potential strategy for development of personalized cancer treatment." (PMID 30158579, 2018). "From a clinical point of view, we identified a group of lung cancer patients with a profile of high PKCα, high Rab37 and low TIMP1 secretion, and this group of patients displayed poor prognosis." (PMID 29312551, 2017). "Finally, we assessed IL-33 expression and Rab37+ST2L+CD206+ M2 macrophage infiltration in lung cancer patients with chemotherapy response data." (PMID 38778059, 2024). "In addition, Pdcd1 expression showed strong positive correlation with Rab37 expression in lung cancer patients, while it was found to be weakly associated with Rab37 in normal tissues (n = 109)." (PMID 38321486, 2024). "Notably, from lung cancer patients showed higher level of Rab37 expression than PBMCs from healthy donors, consistent with our in vitro observation that Rab37 was upregulated in T cells upon cancer CM treatment." (PMID 38321486, 2024). "Rab37 knockout mice and specimens of lung cancer patients were used to validate the concept." (PMID 38321486, 2024).
lung carcinoma (continued). "In addition, in response to lung cancer cells (H460 and H1299 cells) conditioned medium (CM) treatment, Rab37 was upregulated in Jurkat T cells at 24 h and 48 h." (PMID 38321486, 2024). "By contrast, dysfunction of Rab37 or TIMP1 abolishes metastatic suppression of lung cancer cells." (PMID 38695990, 2024). "Moreover, we performed correlation analysis of intratumoral stain intensity of Rab37+/PD-1+/TIM3+/CD8+ T cells with clinicopathological parameters of lung cancer." (PMID 38321486, 2024). "In addition, our previous study has revealed that Rab37 mediates the secretion of sST2 in lung cancer epithelial cells." (PMID 38778059, 2024). "Taken together, these results indicate that high tumor-infiltrating Rab37+/PD-1+/TIM3+/CD8+ T cell level could be used as an independent factor to predict clinical outcome in patients with lung cancer." (PMID 38321486, 2024). "In addition, we identify that the increased infiltration of Rab37+/PD-1+/TIM3+ T cells in tumor serves as a biomarker of poor prognosis in lung cancer patients." (PMID 38321486, 2024). "The results showed that PBMCs from lung cancer patients exhibited significant positive correlation between Rab37 expression and population of PD-1+/TIM3+/CD8+ T cells, which accordingly had negative correlation with anti-tumor activity (GzmB+/IFN-γ+) in CD8+ T cells." (PMID 38321486, 2024). "To further verify the significance of Rab37-mediated PD-1 PM presentation in PBMCs from nine lung cancer patients, we cultured human PBMCs for 7 days and then analyzed Rab37 mRNA expression, PD-1+/TIM3+/CD8+ expression, GzmB+/IFN-γ+/CD8+ expression and cancer cell viability of the PBMCs." (PMID 38321486, 2024). "Similarly, human PBMCs from lung cancer patients with high expression of Rab37 had positive correlation with the population of PD-1+/TIM3+/CD8+ T cell." (PMID 38321486, 2024). "We further detected colocalization of LC3 with either Rab37 or TIMP1, identified Rab37 and Sec22b proteins in the purified autophagosomes of the lung cancer cells harboring the active-form Rab37 gene, and confirmed that these proteins are involved in the secretion of TIMP1." (PMID 36457117, 2022). "We then clarified whether autophagy participates in active-form Rab37-mediated TIMP1 secretion in lung cancer cells." (PMID 36457117, 2022). "Moreover, silencing the Atg5 or Atg7 gene of lung cancer cells harboring active-mutant Rab37 (Q89L) led to decreased autophagy activity and TIMP1 secretion." (PMID 36457117, 2022). "We examined whether the infiltrating M2 tumor associated macrophages (M2 TAM, CD163+) were enriched in the area of Rab37+CHI3L1+ cells in tumor specimens from lung cancer patients." (PMID 34987649, 2022). "PKCα-mediated Rab37 phosphorylation stimulated lung cancer cell motility." (PMID 36358843, 2022). "In this study, we clarified whether starvation could activate Rab37 and induces autophagy simultaneously in lung cancer cells." (PMID 36457117, 2022). "Indeed, downregulation of Rab37 expression seemed to enhance the stem-like properties of lung cancer cells both in vitro and in vivo." (PMID 34072080, 2021). "Moreover, lung cancer patients with low Rab37, low soluble ST2, and low M1/M2 ratio presented worse overall survival." (PMID 34447383, 2021). "Importantly, low expression of Rab37 or SFRP1 was associated with poor overall survival (OS) and progression-free survival (PFS) in lung cancer patients." (PMID 30158579, 2018). "Furthermore, we isolated Rab37-specific intracellular vesicles from PC-14 lung cancer cells by immunoprecipitation (IP) with Flag-tagged antibody followed by immunoblotting to detect SFRP1 protein level." (PMID 30158579, 2018). "Moreover, results of TCF/LEF reporter assay as well as IF and IHC of β-catenin localization confirmed that Rab37 regulated the exocytosis of SFRP1 to inhibit lung cancer stemness properties by attenuating the Wnt signaling components." (PMID 30158579, 2018).